AFP (alpha fetoprotein)
Diseases named in the same sentence as AFP in open-access papers (continued):
Sharing a sentence is not in itself a finding about the gene and the disease.
tumor (continued). "We analyzed the correlation between up-regulated or down-regulated expression of the receptor and ligand in HCC tissue with respect to clinicopathological features (age, gender, tumor size, histological grade, AFP value, microvascular invasion, etc.)." (PMID 29093570, 2017). "Our study including a larger number of eligible studies showed that higher Tregs levels were associated with some clinicopathologic parameters, such as multiple tumors, higher AFP level, poor tumor differentiation, later TNM stage, and vascular invasion." (PMID 28487498, 2017). "In this study, we found that high expression of GFAT1 was significantly associated with serum alpha-fetoprotein (AFP), serum alanine aminotransferase (ALT), tumor size, tumor encapsulation, T stage and TNM stage." (PMID 28186970, 2017). "Based on tumor size > 3.5cm, AFP > 200 ng/ml and GGT > 53U/L, the prediction scoring model are valuable for the preoperative prediction of MVI." (PMID 28977857, 2017). "Our study showed that patients with NAFLD tend to have larger tumour size, but lower AFP level compared to those with HCV." (PMID 27634970, 2017). "AFP values correlated with tumor activity, and it has been shown that AFP is an important determinant of the degree of malignancy of HCC in cytological studies [35, 36, and 37]." (PMID 27880724, 2017). "Compared with other groups, the patients in ZFXhigh/EpCAMhigh groups exhibited much more aggressive clinicopathological features such as AFP, tumor size, tumor number, and tumor differentiation grade." (PMID 28156061, 2017). "Currently, the clinical diagnosis of HCC depends on AFP and imaging examination, such as colour Doppler ultrasound, computed tomography (CT), magnetic resonance imaging (MRI), and tumour cytological biopsy." (PMID 29113334, 2017). "In conclusion, tumor size, albumin, PT, AFP levels were independently associated with mortality after ultrasound-guided RFA for HCC, while tumor size, HBV-DNA, AFP levels before treatment, and AFP response were independently associated with recurrence." (PMID 28679433, 2017). "Results showed that tumor size, albumin, PT, and AFP levels were independently associated with mortality after RFA for HCC, while tumor size, HBV-DNA, AFP levels before, and AFP response were independently associated with recurrence." (PMID 28679433, 2017). "Testing for the hepatitis C virus antibody was positive, and serum tumor markers for HCC were elevated: alpha-fetoprotein (AFP) 13.5 ng/mL, protein induced by vitamin K absence/antagonist-II (PIVKA-II) 68 mAU/mL." (PMID 28843273, 2017). "Immunohistochemical studies of hepatocellular carcinomas showed that decreased CDK10 protein expression levels were significantly correlated with tumor size, alpha-fetoprotein levels, and tumor stage." (PMID 28178678, 2017). "Their tumor markers including alpha-fetoprotein (AFP), beta-human chorionic gonadotropin (β-HCG), cancer antigen 125 (CA-125), lactate dehydrogenase (LDH), and carcinoembryonic antigen (CEA) were all in normal ranges." (PMID 28044991, 2017). "Overall survival (OS) of the T+R and T groups were compared, and sub-group analyses were performed based on baseline α-fetoprotein (AFP) levels, the reduction of AFP, and tumor response before HR." (PMID 27880724, 2017). "LD-1 is related to the characteristic chromosomal abnormality in TGCT, AFP is the main tumor marker used to monitor TC whereas S-hCG is essential in diagnosis and follow-up of hCG producing TGCTs." (PMID 29262668, 2017). "AFP and PIVKA-II have been used previously as useful tumor markers of HCC and are associated with a poor prognosis after hepatectomy." (PMID 28830473, 2017). "As in the present study, the SII was a better prognostic factor than the other indices (PLR, NLR, tumor number, AFP, etc.)." (PMID 29221172, 2017). "The PDEF level was positively correlated with AFP (P=0.016), tumor size (P=0.030), and microvascular invasion (P=0.012)." (PMID 28881746, 2017).
tumor (continued). "The results indicated that AFP, tumor size, TB, A, ALT, AST, GGT, positive for HBVDNA, were significantly different between the 4 groups." (PMID 28700480, 2017). "We observed marked differences in groups of patients according to preoperative platelet count, aspartate aminotransferase (AST) and AFP level, and tumor size." (PMID 29258507, 2017). "Here, we are the first to report that the down-regulation of INTS6 strongly correlates with high AFP levels, poor pathology grades, and tumour recurrence." (PMID 28899352, 2017). "In conclusion, our study by propensity score matching indicated that, single adjuvant TACE after hepatectomy with negative margin was beneficial for patients of AJCC stage I with tumor less than 5cm, or high preoperative AFP or positive of AFP in specimen." (PMID 28460456, 2017). "HCC patients with CXCR4-positive tumor capillaries exhibited significantly higher serum AFP values (p = 0.035) as well as a distinctly higher Ki-67 index (p < 0.001) than those with CXCR4-negative tumor microvessels." (PMID 29282035, 2017). "higher percentage of larger, vascular invading and advanced stage tumours had AFP level over 400 ng/ml." (PMID 29207969, 2017). "In univariate analysis, AFP level, multiple tumor nodules, maximum tumor diameter, number of HCC nodules, UTS criteria and PET-status were significantly associated with risk of HCC recurrence." (PMID 29074969, 2017). "Number of tumors (p = 0.047), size of the largest tumor (p < 0.001), pre-transplant alpha-fetoprotein (p < 0.001), and poor tumor differentiation (p = 0.039) were independent risk factors for HCC recurrence in multivariable analysis." (PMID 28057916, 2017). "In the present study, increments in serum AFP and CEA levels upon DEN induction were associated with increases in tumour development." (PMID 28345375, 2017). "Since AFP is an important clinical tumor marker for HCC growth and aggressiveness, we examined the effects of GSK1838705A and OSI-906 on Regorafenib/VK1-mediated inhibition of AFP secretion levels in HCC cell lines." (PMID 29262576, 2017). "Second, the serological tumor markers AFP and CA19-9 were also significantly different between them." (PMID 29152084, 2017). "And in this nomogram, the tumor stage like tumor size, vascular invasion and pathological differentiation, the tumor marker, like AFP and NLR, the gender and etiology of AYA patients were associated with the long-term survival." (PMID 29290957, 2017). "Logistic regression analysis identified the AFP level as an independent predictor of tumor size (OR, 1.748; 95% CI, 1.574–1.941; P < 0.001)." (PMID 28993684, 2017). "AFP reflects the tumor burden and the Child-Pugh classification reflects liver function: these two factors are HCC-specific and their prognostic values have been confirmed in several previous studies." (PMID 28445959, 2017). "Meanwhile, increased expression of YAP was correlated with larger tumor size (p=0.002), high level of AFP (p=0.024), microscopic vascular invasion (p<0.001) and advanced TNM stage (p<0.001)." (PMID 29245938, 2017). "According to the ROC curves, the optimal cut-offs were: ≥21.4 ng/ml for pre-transplant alpha-fetoprotein concentration, ≥2 for number of tumors, and ≥4 cm for size of the largest tumor." (PMID 28057916, 2017). "Univariate Cox regression analysis revealed that high AFP, poor tumor differentiation, TEPV, and high miR-483-5p expression were significantly associated with both shorter disease-free survival time and shorter overall survival time." (PMID 29245946, 2017). "After being adjusted by AFP > 400ng/mL, Child-Pugh class B, and tumor extension > 50% of the liver, TACE treatment was shown to be an independent prognostic factor associated with a decreased risk of mortality (HR: 0.19; 95% CI: 0.08–0.42; p < 0.01)." (PMID 29190692, 2017).
tumor (continued). "Cirrhosis status and tumor factors, such as tumor staging, multi-nodularity of tumors, AFP levels and an insufficient surgical safe margin, are well known predictors of tumor recurrence after curative resection." (PMID 29176777, 2017). "These analyses did not detect any association with the investigated co-variables (age at diagnosis, tumor histology, alpha-fetoprotein levels, treatment protocol, progression and overall survival)." (PMID 29228658, 2017). "The histology of patient-derived xenograft (PDX)-derived tumor tissues was identical to the original patient’s tumor samples by H&E staining, which was clearly defined by the strong expression of α-fetal protein (AFP), which were well-expressed markers in HCC." (PMID 28635650, 2017). "Basing on the established cutoffs, HCC patients were assigned 1 point for pretransplant alpha-fetoprotein ≥175 ng/mL and 1 point for total tumor volume ≥65.4 cm3." (PMID 28695391, 2017). "We tried to follow the recommended tumor surveillance protocol of AFP and abdominal ultrasonography every 2-3 months for this patient." (PMID 29190888, 2017). "The multivariate model analysis showed that Fib, AFP, macro-vascular invasion, tumor number were independent predictors of DFS (all P < 0.05), whereas Fib, size of largest tumor, macro-vascular invasion were independent predictors of OS (all P < 0.05)." (PMID 27935864, 2017). "In univariate analysis, we initially found several potential prognostic factors (p <0.10), including TACE treatment, AFP > 400ng/mL, Child-Pugh class, and tumor extension > 50% of the liver." (PMID 29190692, 2017). "In the Hangzhou criteria, which expanded the MC for LT, the optimal serum AFP cut-off value for tumor recurrence was revealed to be 400 ng/mL27." (PMID 28276470, 2017). "The tumor marker AFP is widely used for HCC's surveillance, while on account of AFP-negative HCC is frequently observed, AFP-L3 has been a preferred HCC biomarker in early diagnosis of HCC and in predicting prognosis after treatment." (PMID 28736531, 2017). "There was a tendency of positive correlation in the reduction of AFP levels and tumor response identified by MR." (PMID 28166821, 2017). "When the cut-off was determined for the point on the ROC curve that maximizes the sensitivity (52.4%) and specificity (87.5%) by Youden’s index, the optimal AFP cut-off value for tumor recurrence was 321 ng/mL." (PMID 28276470, 2017). "Tumor biomarkers, including alpha fetoprotein (AFP), carbohydrate antigen 19-9 (CA19-9), and carcinoembryonic antigen (CEA), were unremarkable." (PMID 28353562, 2017). "For one thing, we failed to collect some important clinical items for HCC patients, including their AFP values, portal vein invasion statuses and tumor differentiation statuses, which are considered significant elements of the HCC etiology and development." (PMID 28118855, 2017). "By retrospectively investigating preoperative characteristics of patients, We identified three independent predictors for MVI: tumor size > 3.5cm, AFP > 200 ng/ml and GGT > 53U/L." (PMID 28977857, 2017). "The optimal cutoffs for predicting HCC recurrence were 175 ng/mL for alpha-fetoprotein and 65.4 cm3 for total tumor volume." (PMID 28695391, 2017). "High expression of GFAT1 was positively associated with serum AFP (P < 0.001), serum ALT (P < 0.001), tumor size (P < 0.001), tumor encapsulation (P = 0.044), T stage (P < 0.001) and TNM stage (P < 0.001)." (PMID 28186970, 2017). "An AFP elevation > 400ng/ml was also common (~50%), and approximately 60% of patients suffered from a tumor morphology extension > 50% of the liver." (PMID 29190692, 2017). "Size and number of tumor nodules were significantly higher in patients with vascular invasion as was the mean serum AFP level." (PMID 28154760, 2017).
tumor (continued). "In univariate analysis, elevated AFP, γ-GT, low serum albumin, large tumor size, multiple tumors, poor tumor cell differentiation, incomplete tumor encapsulation, advanced BCLC stage, and MVI were associated with both poor OS and poor RFS." (PMID 28095820, 2017). "A prediction scoring system for MVI was built up according to the three independent predictors (tumor size > 3.5 cm, AFP > 200 ng/mL and GGT > 53 U/L)." (PMID 28977857, 2017). "Alpha-fetoprotein (AFP) has been the most commonly used tumor biomarker in the liver, testicles, and ovaries." (PMID 28086821, 2017). "This study documented the reduction of oval cells formation as well as the expression of tumour markers M2-PK, OV-6, AFP and TGF-β in HCC induced rats supplemented with Chlorella vulgaris (ChV)." (PMID 29268718, 2017). "Our study indicated that single postoperative adjuvant TACE was beneficial for selected patients of stage I with tumor less than 5 cm, or high preoperative alpha–fetoprotein in serum or positive of alpha–fetoprotein pathologically." (PMID 28460456, 2017). "The serum levels of tumour markers, namely alpha-fetoprotein (AFP) and carcinoembryonic antigen (CEA), were within normal limits." (PMID 28086809, 2017). "The patients in the vessel group were more frequently classified as larger tumor size (P<0.05) and higher AFP level (P<0.05) than patients in the safe group." (PMID 28430634, 2017). "The Hepa1-6 clone, which was isolated from the BW7756 tumor that arose spontaneously in the C57L/J mouse strain, is widely used, well characterized in vitro and shows high expression of alpha-fetoprotein (AFP)." (PMID 28152020, 2017). "It has been reported that some clinicopathology features, including tumour size, nodule number, macro/μ invasion and pre-operative AFP, are considered as survival indices that affect the prognosis of HCC patients." (PMID 28899352, 2017). "SUVT/L ratio correlates with AFP levels, tumour size and poor differentiation, and should probably be integrated as a co-variable in a predictive outcome model of patients on the waiting-list for liver transplantation." (PMID 26883745, 2016). "There were significant differences in AFP concentration, tumor size, and TNM stage between DCP-negative and DCP-positive subjects (P<0.05)." (PMID 27070780, 2016). "Serum tumor markers (alpha fetoprotein, human chorionic gonadotropin, and lactate dehydrogenase) and computed tomography of the chest and abdomen were negative." (PMID 27293952, 2016). "Tumor characteristics in our nomogram included AFP level, tumor size, tumor number, MVI, major vascular invasion and satellite lesions." (PMID 27811374, 2016). "There were 63 patients who were BCLC stage B and 38 patients who were BCLC stage C. The mean tumor size was 8.2 cm, the mean number of nodules was 3.05, the mean Child Pugh score was 5.54, and the mean baseline AFP was 614.74." (PMID 26769845, 2016). "While the multivariate analysis revealed that AFP value, in together with INR value, GGT value, ALP value and tumor size, were the independent risk factors affecting overall post-surgery survival among those HBsAg positive HCC patients." (PMID 26784252, 2016). "Downregulation of TIP30 in the HCC cases was not correlated with patients’ age, gender, and TNM stages; however, it was inversely correlated with serum HBV infection, serum AFP, and tumor differentiation." (PMID 27418384, 2016). "High-risk patients clearly require close follow-up for early detection of HCC; screening includes tumor markers (AFP) and ultrasound in most centers." (PMID 27403337, 2016). "AFP is a well-established tumor marker for screening and diagnosing HCC, and the AFP level appears to be associated with the prognosis of HCC patients." (PMID 26831408, 2016). "The mediastinum tumor markers (alpha fetoprotein and beta human chorionic gonadotropin) were both normal." (PMID 27144046, 2016).
tumor (continued). "Survival rates have increased in patients who have decrease in serum of AFP after chemotherapy and in cases with residual tumor surgical excision." (PMID 27144043, 2016). "Increased AFP levels (≥ 200 μg/L) were observed in 171 patients (56.4%), and 88 patients (29.0%) had multiple tumor masses." (PMID 27472390, 2016). "Two studies reported the role of post-treatment AFP levels in predicting tumor recurrence and outcomes." (PMID 27304617, 2016). "Different factors have been associated with worse prognosis in patients with HCC undergoing LT, such as serum AFP levels, tumor number, tumor size, degree of differentiation, macro- and microvascular hepatic invasion, outside Milan criteria and infiltration." (PMID 27618033, 2016). "The results indicated that tumor location, tumor size, histological type, T status, N status, CEA, AFP, CA19-9 and CA125 were associated with the prognosis according to the univariate analysis." (PMID 27418046, 2016). "As in earlier studies, the clinical factors including superior liver preservation (score 5), lower AFP, or less aggressive tumor condition remained as the crucial roles to reflect patient results in our study." (PMID 27117280, 2016). "A NLR > 2 was more frequently observed in patients with high serum AFP levels (P = 0.015), with tumor size > 5 cm (P < 0 .001), those with PVTT (P = 0 .026), with recurrence (P = 0.005), with PNI ≤ 45 (P < 0.001) and with PLR > 115 (P < 0.001)." (PMID 26907597, 2016). "High TMED3 expression was associated with positive alpha-fetoprotein (AFP; P = 0.020), larger tumor size (≥5 cm; P = 0.045) and vascular invasion (P < 0.001)." (PMID 27901021, 2016). "There were 40 subjects who were BCLC stage B, and 33 subjects who were BCLC stage C. The mean tumor size was 8.41 cm, the mean number of nodules was 3, the mean Child Pugh score was 5.44, and the mean baseline AFP was 598.82." (PMID 26769845, 2016). "These four HCC patients were selected to represent the heterogeneity of primary HCCs in terms of age, tumor size, serum AFP level and immunohistochemical staining of Hep-1, a marker of differentiation." (PMID 27273737, 2016). "Immunohistochemical staining showed tumor cells with focal positivity for AFP, carcinoembryonic antigen, glypican 3, hepatocyte-specific antigen, protein induced by vitamin K absence or antagonist, and CD56." (PMID 26943677, 2016). "Apparently, patients with HCC have an advantage in the current organ allocation system, when compared with patients without tumor, raising the question of including biological factors of poor prognosis, such as alpha-fetoprotein, and tumor growth rate." (PMID 28076478, 2016). "There were significantly different distributions on etiologies of chronic hepatic diseases, serum biochemistries, α-fetoprotein (AFP) level, coagulation function, and tumor burden among group A, group SL, and group B patients (p<0.05)." (PMID 27176037, 2016). "Univariate Cox proportional hazard regression analysis showed that Brf1 expression (P<0.001), tumor diameter (P=0.007), recurrence (P=0.003), serum AFP (P=0.011) and TNM stages (P<0.001) were significantly associated with overall survival." (PMID 26701855, 2016). "AFP—primarily synthesized in the liver and yolk sac of developing embryo—is also a widely used tumor marker of HCC or germ cell tumor." (PMID 27301956, 2016). "Multivariable analysis showed that risk factors for HCC recurrence included large tumor size (hazard ratio (HR)=1.30, p=0.022), HBV DNA serum level (HR=1.11, p=0.005), and serum AFP level ≥20 ng/mL (HR=1.66, p=0.005)." (PMID 27329596, 2016). "Our univariate analysis indicated that serum AFP level, vascular invasion, intrahepatic metastasis, tumor number, differentiation, AJCC stage and PBLD expression were significant prognostic factors for OS and/or RFS." (PMID 26594798, 2016).